SNORD115-9 (small nucleolar RNA, C/D box 115-9)
Synonyms: HBII-52-9
Gene: Small nucleolar RNA gene on chromosome 15 (25,185,631 to 25,185,712, forward strand). Ensembl gene ENSG00000199782.
Gene Ontology:
Biological process: RNA processing
Cellular component: nucleolus
Homologues: Orthologues: macaque SNORD115 (100% identical). Paralogues in human: SNORD115-12 (100% identical), SNORD115-10 (99% identical), SNORD115-11 (99% identical), SNORD115-13 (99% identical), SNORD115-20 (99% identical), SNORD115-29 (99% identical), SNORD115-36 (99% identical), SNORD115-40 (99% identical), SNORD115-42 (99% identical), SNORD115-43 (99% identical), SNORD115-5 (99% identical), SNORD115-14 (98% identical), and 37 more.